SELENBP1 (selenium binding protein 1)
Diseases named in the same sentence as SELENBP1 in open-access papers (continued):
Sharing a sentence is not in itself a finding about the gene and the disease.
gastric cancer (7 papers, 2014 to 2023). A primary or metastatic malignant neoplasm involving the stomach. "Stomach cancer: SELENBP1 was significantly decreased in a proteomic analysis of gastric cancer specimens." (PMID 36386843, 2022). "Similar results were obtained in gastric cancer, in which SELENBP1 was detected in all cases of nonneoplastic epithelial tissues but was absent in gastric cancer." (PMID 25227434, 2014). "However, we also noticed that PPARG presented a weak negative correlation with SELENBP1 (RHO = −0.24), which has been shown to increase the chemosensitivity of gastric cancer cells." (PMID 34054937, 2021).
lung carcinoma (7 papers, 2014 to 2023). "It has been reported that downregulation of SELENBP1 is often associated with tumour progression in various epithelial cancers, including lung cancer, and with poor clinical outcomes." (PMID 32616892, 2020). "The present study also indicated that the relative mechanisms of SLC34A2 in A549 lung cancer may be associated with the activation of the complement alternative pathway (C3 and C4b) and upregulation of the expression of SELENBP1, TXNIP, PDZK1IP1 and DUSP6." (PMID 25017204, 2014). "Of note, the previous studies reported that the expression of selenium‐binding protein 1 (SELENBP1) was obviously decreased in many human cancer tissues including non‐small cell lung cancer (NSCLC)." (PMID 37606338, 2023). "Lung cancer: SELENBP1 is downregulated in basaloid carcinoma, large cell carcinoma, lung squamous cell carcinoma (LSCC), and adenocarcinoma." (PMID 36386843, 2022). "Previous studies have suggested that SELENBP1 exerts a tumor suppressor function by inhibition of proliferation and was identified as a lung cancer suppressor HIF-1 target gene." (PMID 25017204, 2014). "It is presumed that there are other mechanisms besides epigenetic changes suppressing the expression of SELENBP1, because previous reports showed that downregulation of SELENBP1 is not related to promoter methylation or gene deletion in colon and lung carcinomas." (PMID 32443734, 2020). "We identified SELENBP1 to be down-regulated in cutaneous melanoma, a malignant cancer of pigment-producing melanocytes in the skin, which leads to the assumption that SELENBP1 also functions as tumor suppressor in the skin, as shown by others e.g. for prostate or lung carcinoma." (PMID 29535818, 2018). "SELENBP1 can downregulate HIF-1α protein levels without altering mRNA levels in the human lung carcinoma cell line as well." (PMID 36386843, 2022).
ovarian cancer (6 papers, 2010 to 2023). A primary or metastatic malignant neoplasm involving the ovary. "Reduced SELENBP1 expression has been linked to poor prognosis in several cancers, including lung and ovarian cancers." (PMID 38357363, 2023). "Antibodies to selenium-binding protein 1 (SBP1) have also been identified in ovarian cancer patients, which are characteristic of patients with premature ovarian failure (POF)." (PMID 37446063, 2023). "Ovary cancer: In a membrane proteome profiling analysis, SELENBP1 is decreased in ovary cancer through the selenium/androgen pathway." (PMID 36386843, 2022). "SELENBP1 was previously identified as the most significantly downregulated protein in ovarian cancer cells by membrane proteomics analysis." (PMID 30328513, 2019). "A decrease in the level of selenium binding protein 1 (SBP1) in ovarian cancer cells is observed." (PMID 37446063, 2023). "In addition, high anti-SELENBP1 levels are also observed in patients with serous ovary cancer, which suggests SELENBP1 participates in an autoimmune process during ovary cancer development." (PMID 36386843, 2022). "The downregulation and anti-carcinogenic effects of SELENBP1 are assessed in numerous cancers, including kidney/lung/thyroid/stomach/esophagus/liver/breast/prostate/colon/pancreatic/head and neck/skin/bladder/uterine/nerve and ovary cancer." (PMID 36386843, 2022). "In malignant ovarian cancer, changes in SELENBP1 expression are useful indicators of abnormal selenium/androgen pathways, and such changes may reveal prognostic information relating to ovarian cancer." (PMID 30328513, 2019). "The functions of SELENBP1 are largely unknown; however, it is widely investigated in tumor tissues where it is expressed at lower levels, including in ovarian cancer models." (PMID 31798533, 2019).
colitis (4 papers, 2019 to 2026). Inflammation of the colon. "In mice models, reduced levels of SELENBP1 ameliorated oxidative stress-induced colitis." (PMID 40298842, 2025). "Our results suggest that oxidative stress-induced DNA methylation of miR-122 aggravates colitis targeting SELENBP1 partially by p65NF-κB signaling and may promote the progression of CD." (PMID 31019652, 2019). "Interestingly, transcriptomic analyses revealed that SELENBP1-KO mice exhibited molecular characteristics of colitis (unpublished), which may also contribute to the elevated survival rate seen in SELENBP1-KO septic mice." (PMID 40298842, 2025).
liver cancer (4 papers, 2020 to 2023). An epithelial or non-epithelial malignant neoplasm that arises from the liver. "Higher specificity and sensitivity were obtained when distinguishing liver cancer from normal samples based on the expression level of SELENBP1." (PMID 34493740, 2021). "Liver cancer: The protein level of SELENBP1 is decreased in HCC." (PMID 36386843, 2022). "Further studies are needed to determine the cause of the decrease in SELENBP1 expression in non-HBV liver cancer tissues." (PMID 32443734, 2020). "The downregulation of HIF-1α by SELENBP1 also exists in liver cancer; however, the mechanism is not quite clear yet." (PMID 36386843, 2022).
psychosis (4 papers, 2013 to 2020). "The genes with a down–up type included SELENBP1, MYH9 and an unnamed gene in chromosome 19, both of which are associated with psychotic disorders." (PMID 25407108, 2014).
Sepsis (4 papers, 2013 to 2025). Sepsis is defined as life-threatening organ dysfunction caused by a dysregulated host response to infection. "Collectively, these findings indicate that the Treg/Th17 imbalance induced by SELENBP1-KO mDCs was implicated in the regulation of liver injury during sepsis." (PMID 40298842, 2025). "A previous clinical investigation revealed that elevated urine SELENBP1 levels were associated with poorer outcomes in patients with sepsis." (PMID 40298842, 2025). "Our results describe the immunological involvement of SELENBP1 in sepsis and demonstrate the potential of SELENBP1-deficient DCs as a treatment for sepsis." (PMID 40298842, 2025). "Next, the impact of SELENBP1 deletion on the immunological function of DCs was investigated in vitro, and the efficacy of SELENBP1-deficient DC transfusion in sepsis-infected mice was evaluated." (PMID 40298842, 2025). "Our present study discovered that the enhanced survival rate of sepsis mice with SELENBP1 deletion was associated with a higher Treg/Th17 ratio." (PMID 40298842, 2025). "This indicated that decreased SELENBP1 expression was associated with enhanced survival rates during sepsis." (PMID 40298842, 2025). "Se-binding protein 1 (SELENBP1) is elevated in sepsis, and its deficiency prolongs survival in mice, alleviates hepatic injury, and reduces inflammation, while increasing the splenic Treg/Th17 ratio." (PMID 41216203, 2025). "In summary, our study provides novel insights into how SELENBP1 is implicated in the progression of sepsis via its modulation of DC immunological activity, which may provide a novel way for effective treatment strategies against sepsis." (PMID 40298842, 2025). "In summary, our results indicate that SELENBP1 serves as a biomarker for sepsis; its deficiency induces DCs into a tolerant state by regulating oxidative stress, leading to an increase in the proportion of Treg/Th17, which alleviates liver damage in septic mice." (PMID 40298842, 2025). "The administration of SELENBP1-KO mDCs significantly prolonged the survival time of sepsis-induced mice and resulted in milder liver damage as indicated by histological analyses." (PMID 40298842, 2025). "In this study, we used the GEO database to examine SELENBP1 expression in whole blood and discovered that its levels were significantly higher in sepsis patients." (PMID 40298842, 2025). "We therefore assessed SELENBP1 levels in blood samples from sepsis patients and in liver tissues from septic mice." (PMID 40298842, 2025). "Targeting oxidative stress has shown promise in alleviating tissue damage and acute inflammation resulting from sepsis, as evidenced by findings related to the livers and spleens of LPS-induced SELENBP1-KO mice." (PMID 40298842, 2025). "Here, we detected an elevation of SELENBP1 levels in the blood of sepsis patients and in the livers of septic mice." (PMID 40298842, 2025). "However, further studies are needed to validate the reliability of SELENBP1 as a biomarker for sepsis." (PMID 40298842, 2025). "We hypothesized that SELENBP1 could regulate the immune function of DCs through oxidative stress, potentially leading to the generation of tolDC-like phenotypes suitable for sepsis treatment." (PMID 40298842, 2025). "Additionally, SELENBP1-KO mDCs alleviated liver injury by increasing the Treg/Th17 ratio within the spleen, thereby enhancing the survival of sepsis mice." (PMID 40298842, 2025). "Importantly, elevated levels of SELENBP1 were confirmed in clinical samples obtained from patients diagnosed with sepsis." (PMID 40298842, 2025). "Additionally, a high Treg/Th17 ratio predicted a positive prognosis in sepsis, which was similar to the findings observed within the spleens of LPS-challenged SELENBP1-KO mice." (PMID 40298842, 2025). "In addition, the livers of LPS-induced sepsis mice exhibited dramatically increased SELENBP1 levels." (PMID 40298842, 2025).
Sepsis (continued). "For sepsis prognosis, five proteins were significantly up-regulated: selenium binding protein-1, heparan sulfate proteoglycan-2, alpha-1-B glycoprotein, haptoglobin, and lipocalin; two proteins were significantly down-regulated: lysosome-associated membrane proteins-1 and dipeptidyl peptidase-4." (PMID 23372690, 2013). "Thus, it is worth investigating whether SELENBP1 impacts selenium metabolism and disrupts the expression of selenoproteins, hence influencing the course of sepsis." (PMID 40298842, 2025). "Therefore, the role of SELENBP1 in different tissues during sepsis requires further exploration." (PMID 40298842, 2025). "Therefore, we propose that SELENBP1-KO mDCs may be utilized as a therapeutic strategy for treating sepsis." (PMID 40298842, 2025). "However, whether SELENBP1 effects sepsis by regulating DCs’ function via oxidative stress remains unexplored." (PMID 40298842, 2025). "Moreover, tolDCs resulting from SELENBP1 knockout could be a potential treatment for sepsis." (PMID 40298842, 2025). "However, the role and mechanism of SELENBP1 in sepsis remain unclear." (PMID 40298842, 2025). "However, whether SELENBP1 improves sepsis by regulating immune cell activity remains unknown." (PMID 40298842, 2025). "Although treatment with WT mDCs reduced the SELENBP1 level, increased the Treg/Th17 ratio, and prolonged the survival time of sepsis mice, the therapeutic effect was not satisfactory." (PMID 40298842, 2025).
bipolar disorder (3 papers, 2015 to 2020). A disorder of the brain that causes unusual shifts in mood, energy, activity levels and the ability to carry out day-to-day tasks. "We aimed to validate these findings in a new cohort using real-time PCR in Brodmann's Area (BA) 9, and to determine the disease specificity of increased SELENBP1 expression by measuring SELENBP1 mRNA in subjects with major depressive disorder and bipolar disorder." (PMID 26241353, 2015).
Bladder cancer (3 papers, 2020 to 2023). "The association of SELENBP1 expression, clinicopathological features, and clinical outcome was determined using publicly available dataset from The Cancer Genome Atlas bladder cancer (TCGA-BLCA) cohort." (PMID 31918717, 2020). "Here we show that SELENBP1 is significantly down-regulated in human bladder cancer tissues and cell lines, and its frequent reduction is further associated with tumor progression as well as poor clinical outcome among patients with bladder cancer." (PMID 31918717, 2020). "DNA hypermethylation, especially in the gene body, accounts for the reduction of SELENBP1 expression in bladder cancer." (PMID 36386843, 2022). "To determine the biological function of SELENPB1 in bladder cancer, we firstly employed immunoblotting assay to evaluate SELENBP1 expression in 8 of human bladder cancer cell lines, including T24, T24T, UMUC3, RT4, RT112, TCCSUP, J82 and 5637." (PMID 31918717, 2020). "To determine SELENBP1 expression levels in human bladder cancer, we evaluated the protein expression of SELENBP1 in 12 pairs of bladder cancer tissues and matched adjacent normal tissues using immunoblotting assay." (PMID 31918717, 2020). "Here, we report that the reduction of SELENBP1 is a frequent event and significantly correlates with tumor progression as well as unfavorable prognosis in human bladder cancer." (PMID 31918717, 2020). "As expected, the majority of bladder cancer cell lines exhibited undetectable SELENBP1 protein levels, except TCCSUP and J82 cell lines." (PMID 31918717, 2020). "In the present study, we are the first to show that the reduction of SELENBP1 expression is also a frequent event in human bladder cancer tissues, but is more likely to occur in patients with non-papillary subtype and advanced TNM stage." (PMID 31918717, 2020). "In summary, our results have revealed that the reduction of SELENBP1 is a frequent event and significantly correlates with tumor progression as well as unfavorable prognosis among patients with bladder cancer." (PMID 31918717, 2020). "SELENBP1 protein levels were significantly down-regulated in 9 out of 12 bladder cancers relative to matched adjacent normal tissues (p = 0.0021)." (PMID 31918717, 2020). "Nevertheless, how SELENBP1 is clinically incorporated into bladder cancer management together with other prognostic biomarkers merits further investigation." (PMID 31918717, 2020). "The publicly available TCGA-BLCA data, analyzed by the online MEXPRESS tool, indicates that multiple locations of SELENBP1 gene are hyper-methylated in a majority of bladder cancer tumors." (PMID 31918717, 2020). "Further bioinformatics analysis suggests that DNA hypermethylation, especially in gene body, is likely to account for the reduction of SELENBP1 expression in bladder cancer." (PMID 31918717, 2020). "Bladder cancer: SELENBP1 is significantly downregulated in bladder cancer." (PMID 36386843, 2022). "However, there is no observable effect on this player following the restoration of SELENBP1 in bladder cancer cells." (PMID 31918717, 2020). "Furthermore, restoration of SELENBP1 expression results in a significant G0/G1 phase arrest and subsequent cell growth inhibition in human bladder cancer cells." (PMID 31918717, 2020). "Therefore, how SELENBP1 is clinically incorporated into bladder cancer management merits further investigation." (PMID 31918717, 2020).
Bladder cancer (continued). "Collectively, we report here that SELENBP1 may serve as a promising prognostic biomarker in predicting poor clinical outcome among patients with bladder cancer." (PMID 31918717, 2020). "Intriguingly, this inverse association is much more significant between methylation in gene body and SELENBP1 expression (Pearson r = − 0.619, p < 0.001), suggesting that DNA hypermethylation, especially in gene body, is likely to account for the reduction of SELENBP1 expression in bladder cancer." (PMID 31918717, 2020). "Taken together, our results provide clinical and molecular evidence for an improved understanding of the tumor-suppressive role of SELENBP1 in bladder cancer, suggesting that SELENBP1 could potentially be used as a prognostic biomarker as well as a therapeutic target in future cancer therapy." (PMID 31918717, 2020). "Log-rank test of the OS curves in TCGA-BLCA cohort indicated that bladder cancer patients with low SELENBP1 expression were remarkably related to worse prognosis than those with high SELENBP1 expression, implying that SELENBP1 might serve as a tumor suppressor in bladder cancer." (PMID 31918717, 2020). "We further examined SELENBP1 mRNA levels in The Cancer Genome Atlas bladder cancer (TCGA-BLCA) cohort, including 406 patients with SELENBP1 expression data, in which 19 of patients have SELENBP1 expression data of primary tumor and matched normal bladder tissues." (PMID 31918717, 2020). "Additionally, we also observed that overexpression of SELENBP1 markedly inhibited anchorage-independent growth of UMUC3 cells, further verifying the tumor-suppressive role for SELENBP1 in human bladder cancer cellular transformation." (PMID 31918717, 2020). "Instead, ectopic expression of SELENBP1 pronouncedly attenuates the phosphorylation of c-Jun and STAT1, both of which are indispensable for SELENBP1-mediated transcriptional induction of p21, thereby resulting in the G0/G1 phase cell cycle arrest in bladder cancer cell." (PMID 31918717, 2020). "However, the evidence concerning the clinical relevance of SELENBP1 in human bladder cancer is lacking." (PMID 31918717, 2020). "Nevertheless, the clinical relevance of SELENBP1 in human bladder cancer has not been described in any detail, and the molecular mechanism underlying its inhibitory role in cancer cell growth is largely unknown." (PMID 31918717, 2020). "However, the clinical significance of SELENBP1 in human bladder cancer has not yet been characterized in any detail." (PMID 31918717, 2020).
diabetes (3 papers, 2022 to 2025). "The most significant increase in protein levels was observed for immunoglobulin lambda constant 2 (IGLC2), which increased by 2.29-fold in the diabetes group, while methanethiol oxidase (SELENBP1) showed the most significant decrease in the diabetes group." (PMID 40142159, 2025). "On the other hand, SELENBP1 was devoid of Se in the liver of healthy rats, but Se attached to SELENBP1 after streptozotocin treatment that resulted in development of diabetes." (PMID 37437449, 2023). "The urinary excretion of kidney injury molecule-1 (KIM-1), neutrophil gelatinase-associated lipocalin (NGAL), selenium binding protein 1 (SBP1), and pyruvate kinase M2 (PKM2) was significantly reduced in diabetes rats after administration of the MR extracts." (PMID 35956936, 2022).
lung squamous cell cancer (3 papers, 2013 to 2016). "However, there is little information on expression and function of SELENBP1 during human lung squamous cell cancer (LSCC) carcinogenesis." (PMID 23977169, 2013).
major depressive disorder (3 papers, 2012 to 2015). An episode of depression lasting two or more weeks without an intervening episode of mania. "Nevertheless, a recent study investigated the expression of SELENBP1 in BA46 from 13 subjects with major depressive disorder (MDD), 11 subjects with MDD and psychotic features and 12 controls." (PMID 23805071, 2013).